PJVK (pejvakin)
Description:
Peroxisome-associated protein required to protect auditory hair cells against noise-induced damage. Acts by regulating noise-induced peroxisome proliferation in auditory hair cells and neurons, and promoting autophagic degradation of damaged peroxisomes (pexophagy). Noise overexposure increases reactive oxygen species (ROS) levels, causing oxidative damage to auditory hair cells and resulting in hearing loss. PJVK acts as a ROS sensor that recruits the autophagy machinery to trigger pexophagy of peroxisomes damaged by oxidative stress. In addition to pexophagy, also required to promote peroxisome proliferation in response to sound overstimulation.
Synonyms: DFNB59
Tractability: No criterion of Open Targets' tractability assessment is met for any kind of drug.
Gene: Protein-coding gene on chromosome 2 (178,451,346 to 178,462,102, forward strand). Ensembl gene ENSG00000204311.
Subcellular location: Peroxisome membrane; Cell projection, cilium
Pathways (Reactome):
Sensory Perception: Sensory processing of sound by inner hair cells of the cochlea; Sensory processing of sound by outer hair cells of the cochlea
Gene Ontology:
Biological process: pexophagy; programmed cell death in response to reactive oxygen species; regulation of peroxisome organization; response to reactive oxygen species; sensory perception of sound; programmed cell death
Cellular component: cytoplasm; neuronal cell body; peroxisomal membrane; ciliary rootlet; cilium; cortical actin cytoskeleton; stereocilium base
Genetic constraint (gnomAD): Loss-of-function variants: 29 observed, 33.68 expected, observed/expected ratio (o/e) 0.86, 90% interval 0.64 to 1.17. The upper end of that interval is the gene's LOEUF score, 1.17, which puts it in group 5 of 6, group 1 being the genes least tolerant of losing a copy. Missense variants: 403 observed, 430.94 expected, observed/expected ratio (o/e) 0.94, 90% interval 0.86 to 1.01. Synonymous variants: 140 observed, 151.09 expected, observed/expected ratio (o/e) 0.93, 90% interval 0.81 to 1.07.
Gene-disease validity (ClinGen):
ClinGen rates the evidence that PJVK causes each of these diseases.
nonsyndromic genetic hearing loss (autosomal recessive): Definitive. A disease characterized by hearing loss that is not part of a larger syndrome.
Homologues: Orthologues: macaque PJVK (100% identical), chimpanzee PJVK (99% identical), guinea pig PJVK (98% identical), dog PJVK (98% identical), pig PJVK (97% identical), mouse Pjvk (96% identical), rat Pjvk (95% identical), rabbit PJVK (88% identical), tropical clawed frog pjvk (75% identical). Paralogues in human: GSDMD (19% identical), GSDMA (18% identical), GSDMC (17% identical), GSDMB (16% identical).
Diseases named in the same sentence as PJVK in open-access papers:
PJVK is named in the same sentence as 24 diseases in open-access papers, as found by Europe PMC text mining. Sharing a sentence is not in itself a finding about the gene and the disease. The quoted sentences say what the papers report.
deafness (15 papers, 2017 to 2025). An inherited or acquired condition characterized by the complete loss of the ability to hear from one or both ears. "Previous studies have demonstrated that all known mutations in PJVK are associated with deafness, but few studies have shown a link between PJVK and cancer." (PMID 35784306, 2022). "However, the first reference describing a member of this family appeared in 1999 in a review on hereditary hearing loss and deafness in which pejvakin (PJVK), a protein currently known as gasdermin F, was mentioned." (PMID 37627547, 2023). "Interestingly, of 118 deafness genes, several genes have been reported to be associated with auditory neuropathy, a hearing dysfunction characterized by impaired transmission of signal to the auditory nerve by the presynaptic inner hair cells, such as PJVK, NARS2, SLC17A8, DIAPH3 and DIAPH1." (PMID 37062025, 2023). "The GSDM family consists of GSDMA, GSDMB, GSDMC, GSDMD, GSDME (or deafness, autosomal dominant 5, DFNA5), and DFNB59 (or pejvakin)." (PMID 38711020, 2024). "In mice, the pejvakin protein (mm-PJVK) is able to affect the autophagy of peroxisomes in auditory hair cells and protect them against damage, which explains its role in deafness." (PMID 34996441, 2022). "Six types of GSDMs paralogous genes, namely GSDMA, GSDMB, GSDMC, GSDMD, and GSDME [also termed deafness, autosomal dominant 53 (DFNA5)], and pejvakin [PJVK; also termed deafness, autosomal recessive 59 9DFNB59)], have been found in humans." (PMID 36003332, 2022). "The gasdermin family consists of six members: GSDMA, GSDMB, GSDMC, GSDMD, GSDME (also called DFNA5 (deafness, autosomal dominant 5)), and DFNB59 (also known as pejvakin)." (PMID 34522213, 2021).
hearing loss (11 papers, 2011 to 2025). "PJVK gene was recently shown to create hypervulnerability to sound in humans and was the first human gene implicated in non-syndromic hearing impairment due to neural defect." (PMID 39230647, 2025). "Previous studies have also shown that PJVK variants affected cell signaling in hair cells and sensory neurons and appeared to cause severe to profound hearing impairment." (PMID 39230647, 2025). "As a result, we can assume that the hearing impairment diagnosed in our patient was caused by the formation of a truncated PJVK protein through alteration of the transcript splicing site." (PMID 39230647, 2025). "Recessive PJVK mutations that cause a deficiency of pejvakin, a protein expressed in both sensory hair cells and first-order neurons of the inner ear, are an important cause of hereditary hearing impairment." (PMID 36278489, 2022). "Here we report the first European cases of DFNB59 hearing impairment, including four novel pathogenic variants that expand the mutational spectrum of PJVK." (PMID 35052489, 2022). "Five PJVK pathogenic variants, four of them novel, were found in three unrelated cases whose clinical characterization further illustrates the phenotypic variability of the PJVK type of hearing impairment." (PMID 35052489, 2022). "DFNB59 or PJVK is a protein related to hearing impairment or loss in humans and mice." (PMID 35795683, 2022). "Given these concordant data on the involvement of PJVK gene in hearing impairment, we next investigated the implication of this gene in Mauritanian patients negative for the GJB2 and LRTOMT genes." (PMID 39230647, 2025). "Humans and mice express GSDMF/GsdmF (also termed pejvakin/PJVK or DFNB59), which shares sequence and functional similarity with GSDME because mutations of both of these genes cause hearing loss in humans." (PMID 37771587, 2023). "Another protein, pejvakin, has been reported to be involved in hearing impairment via the degradation of peroxisomes, although another group studying a different pejvakin mutation found that the link with peroxisomes was unclear." (PMID 36291074, 2022). "We report here the identification of a novel splice site pathogenic variant in the PJVK (DFNB59) gene in a Mauritanian child affected by prelingual non-syndromic hearing impairment." (PMID 39230647, 2025). "Mutations in OTOF and PJVK genes cause DFNB9 and DFNB59 types of hearing loss, respectively." (PMID 21935370, 2011). "No pathogenic variants in PJVK associated with DFNB59 hearing loss were identified." (PMID 40346465, 2025).
auditory neuropathy (6 papers, 2013 to 2024). A hearing disorder characterized by impaired transmission of signals through the auditory nerve, resulting in mild to severe hearing loss and poor speech perception. "Pjvk encodes the protein pejvakin, and mutations in the gene cause auditory neuropathy in humans and vestibular defects in mice." (PMID 23755015, 2013). "Firstly, pejvakin (PJVK or DFNB59), located at chromosome 2q31.1–q31.3, was identified in patients with auditory neuropathy." (PMID 33033617, 2020).
autosomal recessive deafness (3 papers, 2020 to 2025). "Nonsense mutations in the PJVK gene encoding protein PJVK, which is present in hair cells supporting cells and spiral ganglion cells, resulted in autosomal recessive nonsyndromic deafness in humans at the DFNB59 locus on chromosome 2q31.2." (PMID 33187328, 2020). "Mutations inPJVK cause autosomal recessive hearing loss (DFNB59), and Pejvakin modulates actin dynamics to sustain OHC activity and survival in a cell-autonomous manner, which may depend on its interaction with ROCK2 and other Rho effectors." (PMID 40391522, 2025).
glioma (3 papers, 2021 to 2022). A benign or malignant brain and spinal cord tumor that arises from glial cells (astrocytes, oligodendrocytes, ependymal cells). "Our study shows that GSDMC, GSDMD, and PJVK have transcriptional heterogeneity and are associated with glioma prognosis." (PMID 35784306, 2022).
ovarian carcinoma (3 papers, 2022 to 2023). A malignant neoplasm originating from the surface ovarian epithelium. "However, some PYAGs with CNV gain, such as GSDMD, TP63, PRKACA, PJVK and CASP4, showed downregulated mRNA expression in ovarian cancers, and some PYAGs with CNV loss, such as IL18, GPX4, GZMA, NLRP6 and CASP6, showed upregulated mRNA expression in ovarian cancers." (PMID 36707884, 2023). "provided a novel gene signature including 7 PRGs (AIM2, PLCG1, ELANE, PJVK, CASP3, CASP6, and GSDMA) for predicting the prognosis of ovarian cancer (OC) patients and laid a foundation for further studies of the relationships between PRGs and immunity in OC." (PMID 35912258, 2022).
colorectal tumors (1 paper, 2025). "We found that the transcriptional levels of GSDMA, GSDMC, and PJVK were significantly increased in human colorectal tumors; while, the expression of GSDMB, GSDMD, and GSDME remained unchanged." (PMID 40213993, 2025).
cutaneous melanoma (1 paper, 2022). A primary melanoma arising from atypical melanocytes in the skin. "Intrahepatic cholangiocarcinoma, cutaneous melanoma, uterine endometrioid carcinoma and uterine mixed endometrial carcinoma had the highest GSDMA (6.67%), GSDMB (2.7%), GSDME (6.52%) and PJVK (4.76%) mutation frequency, respectively." (PMID 35164740, 2022).
hepatic carcinoma (1 paper, 2025). "Additionally, GSDMA, GSDMC and PJVK were lowly expressed in hepatic carcinoma cells, especially GSDMA." (PMID 39816682, 2025).
serous ovarian cancer (1 paper, 2021). "In serous ovarian cancer, the PJVK expression is downregulated, but its significance in tumors is unclear and needs further investigation." (PMID 34938319, 2021).
uterine endometrioid carcinoma (1 paper, 2022). "GSDME and PJVK mutation were related to uterine endometrioid carcinoma and uterine mixed endometrial carcinoma, respectively." (PMID 35164740, 2022).
tumor (29 papers, 2020 to 2025). "But the mRNA expression level of PJVK was negatively related to tumor stage, and the higher the tumor stage, the lower its expression level." (PMID 35321945, 2022). "We found that PJVK was downregulated in tumour tissues, and its low expression predicted poor survival rates, indicating that it functioned as a tumour suppressor gene in this study." (PMID 33828074, 2021). "GSDMC and PJVK expression levels in tumor grade 1 and 3 differed from normal tissues, respectively." (PMID 39607202, 2024). "PJVK was also confirmed to participate in tumor immune microenvironment remodeling." (PMID 35922531, 2022). "Notably, PJVK expression was negatively correlated with the level of immune infiltration but positively correlated with tumor purity." (PMID 36003332, 2022). "Among that, 33 PRGs were upregulated, while NLRP1 and PJVK was downregulated in tumor samples." (PMID 35000541, 2022). "Interestingly, previous results confirmed that the expression of GSDMA/B/D/E was significantly elevated in tumor tissues, while PJVK was downregulated." (PMID 35321945, 2022). "In LIHC, correlation analysis of gasdermin family gene expression with tumor microenvironment revealed that GSDMA and GSDMC expressions were positively related to stromal score, whereas GSDMB and PJVK expressions were negatively associated with the stromal score." (PMID 35922531, 2022). "We found high PJVK expression in tumor tissues from patients with a relatively poor prognosis." (PMID 34627252, 2021). "Further studies may focus on whether/how PJVK participates in pyroptosis and tumour suppression." (PMID 33828074, 2021). "Based on the analysis of UALCAN, the expression of all GSDM family members was increased in tumor-stage 1–3 subgroups, and the expression of GSDMA, GSDMB, GSDMC, and PJVK was higher in all four tumor-stage subgroups than in normal subgroups." (PMID 36505798, 2022). "A total of 24 pyroptosis-related genes shown significantly different expression between normal and tumor tissues in COAD and seven genes (CASP4, CASP5, CASP9, IL6, NOD1, PJVK, and PRKACA) screened by univariate and LASSO cox regression analysis were used to construct the risk model." (PMID 34938319, 2021). "GSDMA, GSDMC and PJVK are not detected in most human tissues (both tumor tissues and normal tissues), while GSDMB, GSDMD and GSDME are highly expressed in most human tissues (both tumor tissues and normal tissues), especially GSDMD." (PMID 34421915, 2021).
cancer (9 papers, 2021 to 2025). A tumor composed of atypical neoplastic, often pleomorphic cells that invade other tissues. "High expressions of GSDME and PJVK were associated with subtype C5, indicating these two genes might mainly play a cancer suppressor role." (PMID 35164740, 2022). "Here, we found that high PJVK expression correlates with favorable OS, indicating that further exploration of the role of PJVK in cancer development and treatment has broad prospects." (PMID 35784306, 2022). "Six GSDM family genes (i.e., GSDMA, GSDMB, GSDMC, GSDMD, GSDME, and PJVK) have long been described in other fields; however, they have been rarely investigated in a pan-cancer setting." (PMID 36003332, 2022). "The GSDM family includes six members, GSDMA, GSDMB, GSDMC, GSDMD, GSDME (DFNA5), and PJVK (Pejvakin, DFNB59), which can induce pyroptosis, thereby regulating the tumorigenesis of various cancers." (PMID 36505798, 2022). "Finally, PJVK showed significant differences in mRNA expression at different clinical stages of BRCA, KIRP, LUAD, and LUSC, while lower PJVK expression levels were observed in the more advanced stages of these cancers." (PMID 36003332, 2022). "GSDMA, GSDMC, and PJVK were expressed at low levels in all cancers." (PMID 35922531, 2022). "Overall, the NLRP3, PJVK, TIRAP, IL18, NLRP1 and NLRP6 genes were thought to protect against cancer, while the rest of the pyroptosis genes seemed to be correlated with cancer risk." (PMID 35246158, 2022). "Protein kinase CAMP-activated catalytic subunit alpha (PRKACA), elastase neutrophil expressed (ELANE), NLRP1, pejvakin (PJVK), and CASP9 were significantly downregulated in 25, 24, 22, 25, and 23 types of cancers, respectively." (PMID 35246158, 2022).
infection (2 papers, 2020 to 2022). The state of being infected such as from the introduction of a foreign agent such as serum, vaccine, antigenic substance or organism. "We also showed that one gasdermin family member, pejvakin, lost its pore-forming functionality, but that all gasdermin family members, including pejvakin, likely retained a role in inflammation and the physiological response to infection." (PMID 34996441, 2022).
PJVK also shares sentences with these, for which no sentence is quoted: Hearing impairment (5 papers); autosomal recessive hearing loss (2); Cognitive impairment (1); COVID-19 (1); genetic disorders (1); intrahepatic cholangiocarcinoma (1); lymph node metastasis (1); prostate carcinoma (1); rectal cancer (1); Usher syndrome (1).